STAT1 (signal transducer and activator of transcription 1)
Diseases named in the same sentence as STAT1 in open-access papers (continued):
Sharing a sentence is not in itself a finding about the gene and the disease.
toxoplasmosis (12 papers, 2014 to 2025). A parasitic disease contracted by the ingestion or fetal transmission of toxoplasma gondii. "Analysis of overlapping downregulated DEGs in the leishmaniasis and toxoplasmosis pathways identified key association with Tnf, Mapk11, Tbfb3, Stat1, and MHC Class II-related genes (H2-Oa, H2-DMb1, H2-Aa, H2-Dma, H2-Eb1, and H2-Ab1)." (PMID 40206211, 2025). "As well, phosphorylation of STAT1 has been reported in acute mouse toxoplasmosis and Salmonella infection with activation of caspase 8 and host cell death." (PMID 37759313, 2023). "The relationships between toxoplasmosis, in which STAT1 and IRF1 were highly involved, and ASD have been widely studied." (PMID 34946850, 2021). "Patients with an autosomal dominant defect in IFN-γR1 resulting in deletion of the signal transducer and activator of transcription 1 (STAT1) binding site are not susceptible to toxoplasmosis, although their macrophages are unable to display anti-T. gondii activity in response to IFN-γ." (PMID 37064813, 2023). "Furthermore, in a series of 115 patients with IFN-γR1, IFN-γR2, and STAT1-deficiencies, respectively, only one single patient developed clinical toxoplasmosis and among 141 patients with IL-12Rβ1deficiency no single patient developed toxoplasmosis." (PMID 30873157, 2019). "In the KEGG results, we found that DF‐related genes, STAT1 and IL12A, were enriched in the signaling pathway of ‘toxoplasmosis’, and MAGED1 was enriched in ‘protein processing in endoplasmic reticulum’." (PMID 30868055, 2019). "In addition, STAT1-independent artificial induction of IDO1 could evade the TgIST-dependent virulence mechanism and offer a novel therapeutic strategy for treating human toxoplasmosis." (PMID 30283439, 2018).
experimental autoimmune encephalomyelitis (11 papers, 2006 to 2025). An autoimmune demyelinating disease of the central nervous system that is produced experimentally in animals by the injection of homogenized brain or spinal cord in Freund's adjuvant. "The authors suggest that the increased susceptibility to experimental autoimmune encephalomyelitis is related to impaired function of regulatory T cells, which is STAT-1-dependent." (PMID 16507120, 2006). "Next, we asked if Stat1 is likewise activated under disease conditions, such experimental autoimmune encephalomyelitis (EAE), a model of MS." (PMID 37663126, 2023). "Another study has suggested that experimental autoimmune encephalomyelitis (EAE) induced IFN-γ signaling that can have a protective effect through STAT1 in immune cells of the CNS49." (PMID 36841839, 2023). "A previous study showed that there is residual T-bet protein in the Th cells of STAT1 KO mice that may allow for the induction of IFN-γ leading to experimental autoimmune encephalomyelitis (EAE)." (PMID 34943969, 2021). "In animal models of experimental autoimmune encephalomyelitis (EAE), baricitinib was confirmed to act as a JAK1/2 inhibitor, delays disease onset, mitigates symptom severity, and inhibits Th1/Th17 polarization alongside STAT1/3/4 phosphorylation." (PMID 41585231, 2025). "A published study on experimental autoimmune encephalomyelitis indicated that STAT1 and STAT3, but not STAT5, regulated IL-9 mediated IL-17 production in T cells." (PMID 29887863, 2018). "IL-27 can also exert anti-inflammatory effects, through inhibiting the generation of T cells into its subset Th17 via signal transducer and activator of transcription 1 (STAT1) and STAT3 signaling pathways, thus alleviating the symptoms of experimental autoimmune encephalomyelitis (EAE)." (PMID 28612255, 2017).
hyper-IgE syndrome (11 papers, 2015 to 2025). A condition that is characterized by elevated serum IgE, dermatitis, and respiratory infections. "In contrast, disseminated histoplasmosis occurred in IL-12Rβ1 deficiency, IFN-γR1 deficiency, and GOF STAT1 defect, but 7 out of 10 cases of histoplasmosis in hyper-IgE syndrome involved the aerodigestive tract only." (PMID 28702025, 2017). "Through our APID Network and literature search, the types of PIDs that have been documented in children with T. marneffei infection include CD40L deficiency, AD hyper-IgE syndrome, GOF STAT1 disorder and AD IFN-γR1 deficiency." (PMID 31572394, 2019). "The observation that hyper-IgE syndrome caused by STAT3 loss-of-function mutations and EoE share some similar symptoms including atopic manifestations suggests that both diseases are triggered by an impaired balance between STAT1 and STAT3 activation." (PMID 40775363, 2025). "Most recently-reported children patients are also HIV-negative, and more infected children were revealed to have IEIs, such as hyperimmunoglobulin M syndrome (HIGM), hyper-IgE syndrome (HIES), and STAT1 gain-of-function (GOF) disorder." (PMID 36180657, 2022).
ischemia (11 papers, 2012 to 2025). A hypoperfusion of the BLOOD through an organ or tissue caused by a PATHOLOGIC CONSTRICTION or obstruction of its BLOOD VESSELS, or an absence of BLOOD CIRCULATION. "Some of these regulators have been already associated with different forms of ischemia (e.g. Creb, Stat1, Bcl6, miR-122, miR-21, miR-214, miR-493) while others have not (e.g. Maf, Nptx1, Lef1, miR-290, miR-297, miR-466)." (PMID 29121052, 2017). "Stat1 was previously shown to be a pathological effector in the heart, as loss of this gene protected the heart after ischemia injury." (PMID 27764156, 2016). "In terms of its potential role in ophthalmic diseases, a previous study has found the opposite effect of the Scfd2 gene on STAT1 and miR-493 regulators, which are associated with ischemia, a type of common pathological pathway for neuronal cell degeneration associated with many retinal diseases." (PMID 36009466, 2022). "Phosphorylated STAT1 can exacerbate ischemia-induced neuronal injury, while STAT1 knockout can decrease cerebral infarction volume in mice." (PMID 37361996, 2023). "Besides, IL-1R2-overexpressed mice reduced the expressions of p-STAT1, IL-17RA, Bax, and in heart from mice with 45 min of ischemia followed by 3 h of reperfusion." (PMID 35087030, 2022). "Activated (pY701) STAT1 is upregulated in rat brain during focal cerebral ischemia-reperfusion experiments and localizes to the core of lesions, indicating that it may play a role in cell death during ischemia-reperfusion." (PMID 22938163, 2012). "STAT1, STAT3, and STAT6 are all involved in the activation of microglia induced by ischemia." (PMID 37361996, 2023). "Thymosin β4 may protect the myocardium by downregulating STAT1 and upregulating STAT3 expression and inhibiting myocardial apoptosis induced by ischemia and reperfusion after severe scald injury." (PMID 35281544, 2022). "Thymosin β4 may protect the myocardium by downregulating STAT1 mRNA expression and upregulating STAT3 mRNA expression and inhibiting myocardial apoptosis induced by ischemia and reperfusion after severe scald injury." (PMID 35281544, 2022).
nasopharyngeal carcinoma (11 papers, 2014 to 2024). A carcinoma arising from the nasopharyngeal epithelium. "Previous studies have demonstrated the inhibition of IFNγ-dependent phosphorylation of STAT1 by butyrate, in a nasopharyngeal carcinoma model." (PMID 30619249, 2018). "In nasopharyngeal carcinoma, SENP1 increases STAT1 protein level and promotes its nuclear translocation by inhibiting STAT1 SUMOylation, resulting in cancer invasion and metastasis." (PMID 38389923, 2024). "In nasopharyngeal carcinoma, LINC00669 protects SOCS1 from ubiquitinating STAT1, which promotes cancer cell proliferation and invasion." (PMID 34527677, 2021). "In this study, by constitutive silencing STAT1 in human radioresistant nasopharyngeal carcinoma CNE-2R cell line, we showed that inhibition of STAT1 enhanced radiosensitivity of CNE-2R." (PMID 29492196, 2018). "Also, sodium butyrate has been described to inhibit STAT1 signaling and to upregulate IDO ubiquitination in human nasopharyngeal cancer cell lines." (PMID 24911872, 2014).
renal carcinoma (11 papers, 2002 to 2025). A carcinoma arising from the epithelium of the renal parenchyma or the renal pelvis. "Particularly in renal carcinoma, increased STAT1 expression was associated with high grade, later stage, large tumor size, and lymph node and distant metastasis." (PMID 35440542, 2022). "By targeting both TNKS1 and CDK8, TCS9725 is expected to disrupt critical signaling pathways involved in renal cancer progression, including STAT1, β-Catenin, and TGFβ1-Smad signaling, which are known to drive cancer cell proliferation and metastasis." (PMID 40699862, 2025). "Our results also suggested that JNK and STAT1 signaling were possible signaling pathways that contributed to CALCR-mediated renal carcinoma progression." (PMID 38985127, 2024). "A variety of studies have shown that upregulation STAT1 expression is related to radio-resistance in many tumors, such as renal carcinoma cells, myeloma cell line, and breast cancer." (PMID 29492196, 2018). "Knockdown of IFI35 could inhibit the proliferation and invasion of renal cancer cells by enhancing the STAT1/STAT6 phosphorylation (pSTAT1/pSTAT6)-dependent autophagy." (PMID 35740527, 2022). "Additionally, blockade of STAT1/STAT6 phosphorylation (pSTAT1/pSTAT6) abrogated the induced autophagy by IFI35 knockdown in renal cancer cells." (PMID 35740527, 2022). "To detect whether these signaling pathways were required for IFI35-mediated autophagy, we first detected phosphorylated expression levels of STAT1/STAT6 in IFI35 shRNA-treated renal cancer cells." (PMID 35740527, 2022). "The results demonstrated that knockdown of IFI35 could inhibit the proliferation and invasion of renal cancer cells by enhancing the STAT1/STAT6 phosphorylation (pSTAT1/pSTAT6)-dependent autophagy." (PMID 35740527, 2022). "In renal cancer cells, down-regulation of STAT1 expression induced cell grew more slowly." (PMID 29492196, 2018). "In renal carcinoma cells, IL-22 suppresses cell growth in a dose dependent manner and inhibits the growth of tumor xenografts; these effects were in part mediated through regulation of STAT1 and ERK1/2 signaling pathways." (PMID 25793261, 2015). "We found that the phosphorylation of c-jun (P = 0.002) and STAT1 (P = 0.032) was significantly inhibited in CALCR-depleted cells compared to the respective control cells, reminding that c-jun and STAT1 related signaling pathways may be involved in CALCR induced renal carcinoma development." (PMID 38985127, 2024). "Moreover, inactivation of PBRM1/BAF180 reduced IFNγ-STAT1 activity in renal carcinoma." (PMID 34865122, 2021).
Alzheimer disease (10 papers, 2016 to 2026). A progressive, neurodegenerative disease characterized by loss of function and death of nerve cells in several areas of the brain leading to loss of cognitive function such as memory and language. "This study aimed to explore the effect of microRNA (miR)-146a inhibition on regulating cell apoptosis, total neurite outgrowth, inflammation, and STAT1/MYC pathway in Alzheimer's disease (AD)." (PMID 33729395, 2021). "The miRNA hsa-miR-146a is crucial for the progression of Alzheimer’s disease and functions through the hsa-miR-146a/STAT1/MYC pathway." (PMID 28970833, 2017). "In summary, this study we have also identified important genes (NRG1, NEDD9, IRF5, IFI35, STAT1, STAT2, JAK2, IL3RA), and alterations in biological processes and pathways that may be associated with Alzheimer’s Disease." (PMID 34484988, 2021). "The functions of STAT1 are mainly related to cell adhesion molecules (CAMs), ECM receptor interaction, focal adhesion, Parkinson's disease, and Alzheimer's disease." (PMID 35003395, 2021). "A study on Alzheimer’s disease (AD) showed that apigenin and luteolin can decrease CD40 expression on the surface of microglial cells by investigating the upstream signal transducer and activator of transcription (STAT1) signaling pathway." (PMID 41515450, 2026). "In addition, studies have uncovered the molecular interactions between compounds derived from Sanghuangporus and Alzheimer’s disease; within Sanghuangporus, 374 disease-related targets have been identified, including crucial ones such as JAK1, LCK, MAPK1, STAT3, and STAT1." (PMID 39997416, 2025).
cryptococcosis (10 papers, 2018 to 2024). An acute or chronic, localized or disseminated infection by Cryptococcus neoformans. "We report that this CMC pediatric patient with a new STAT1 gene mutation site had superficial cutaneous fungal infection, as well as intracranial and hematogenous cryptococcal infection." (PMID 40625894, 2024). "We uncovered novel roles for neutrophils and monocytes as coordinators of a STAT1-dependent cascade of responses that mediate vaccine-induced protection against invasive cryptococcosis." (PMID 39324785, 2024). "Our patient presented lower memory B lymphocytes and impaired B-cell differentiation, common with a STAT1 R274W patient with disseminated Cryptococcosis." (PMID 36891307, 2023). "STAT1 gain of function CMC complicated with cryptococcal infection is rarely reported." (PMID 40625894, 2024). "Among them, some patients carrying heterozygous STAT1 GOF mutations were found with cryptococcosis." (PMID 35558066, 2022). "Similarly, a previous study indicated that STAT1 was involved in Cryptococcus neoformans infection in BALB/c mice." (PMID 29849669, 2018).
hepatitis C (10 papers, 2013 to 2025). "Meanwhile, another research showed that the expression levels of STAT1 were increased in hepatitis C patients, even higher than that of MASH patients." (PMID 39605886, 2024). "In hepatitis C virus infection, the viral core protein increased STAT1 acetylation and blocked its phosphorylation by decreasing the transcription level of HDAC4, resulting in reduced host immune responses to IFN-α stimulation." (PMID 37052505, 2023). "Suppression and impairment of anti-viral activity of interferon α (IFNα) has been shown in hepatitis C infection through inhibition of Jak1/Tyk2/STAT1 phosphorylation and upregulation of PP2A dependent upon NS5A protein." (PMID 29447178, 2018). "STAT1 expression and induction of STAT1-phosphorylation has been shown to be enhanced in NK cells of patients with hepatitis C which is then further increased by IFNa therapy, potentially leading to a more cytotoxic phenotype." (PMID 24751903, 2014). "Previously, we showed that lymphotropic HCV could suppress IFN-γ/STAT-1/T-bet signaling, which could contribute to the persistence of hepatitis C virus infection." (PMID 24905921, 2014). "Furthermore, the cross-talk between PD-1 and the suppressor of cytokine signaling-1 negatively regulates IL-12 expression by limiting STAT1 phosphorylation in monocytes/macrophages from hepatitis C virus infection." (PMID 24853068, 2014). "We selected two target proteins (CCL2 and STAT1) with the strongest regulatory interaction with NASH and hepatitis C for molecular docking analysis to predict their potential therapeutic effects." (PMID 39605886, 2024). "Combined with our analysis, STAT1 could be an important cross-talk gene between MASH and hepatitis C." (PMID 39605886, 2024). "When reviewing both of the original publications,the STAT1 ChIPx study (Robertsonet al., 2007) and the study that generated the gene expressionprofiles from hepatitis C-infected PBMCs (Tayloret al., 2007), we found that neither study had reported thisfinding." (PMID 23457041, 2013).
metastatic melanoma (10 papers, 2010 to 2025). A melanoma that has spread from its primary site to another anatomic site. "Taken together, these findings indicate that, although STAT5 activation is normal in metastatic melanoma patients in response to IL-2, indirect STAT1 activation is defective owing to deficiencies in the NK cell response to IL-2." (PMID 27153543, 2016). "Here, we measured the extent of HD IL-2-induced phosphorylation of STAT5 and STAT1 in lymphocyte subsets from metastatic melanoma patients and healthy controls at a single cell level using flow cytometry." (PMID 27153543, 2016). "Taken together, our data suggest that an impaired IFN-γ secretion by NK cells was responsible for the defective STAT1 activation in NK and T lymphocytes from metastatic melanoma patient in response to IL-2." (PMID 27153543, 2016). "In concurrent studies with our own, it was recently shown that STAT1 is silenced in two additional metastatic melanoma cell lines, SK-Mel-28 and MM96." (PMID 25690042, 2015). "To investigate if the observations seen in vitro mirror the metastatic melanoma samples, we examined STAT1 expression levels in patient tumor samples." (PMID 25690042, 2015). "We are currently investigating the molecular mechanisms by which STAT1 is suppressed in metastatic melanoma." (PMID 25690042, 2015). "STAT1 expression has also been found to correlate with a favorable prognosis in several cancer types, including colorectal, hepatocellular and esophageal cancers, and metastatic melanomas." (PMID 35781872, 2022). "In this study, we measured the extent of STAT5 and STAT1 activation, proliferative capacity and cytokine production in different peripheral blood lymphocyte subsets from a group of patients with metastatic melanoma in comparison to a cohort of healthy controls upon HD IL-2 stimulation." (PMID 27153543, 2016). "By investigating STAT1 expression in patient tumors, oncologists may be able to employ targeted immunotherapies, thus increasing a patient’s immune response to metastatic melanoma." (PMID 25690042, 2015). "By activating STAT1/IRF1 signaling through IFN-γ in tumor-associated macrophages, SP140 promotes PD-L1 expression, which has been reported as both a therapeutic target and a predictive biomarker of immunotherapy response in cancers such as metastatic melanoma and head and neck neoplasms." (PMID 41188771, 2025). "We evaluated the correlation of EVI2B gene expression in metastatic melanoma samples with the IFN-γ related gene signature (CXCL10, CXCL9, HLA-DRA, IDO1, IFNG, and STAT1)." (PMID 34439264, 2021). "Interestingly, we also found that the defect in STAT1 activation in CD4+ T cells and NK cell subsets in the patients with metastatic melanoma was age-related, while normal donors had a stable response with age." (PMID 27153543, 2016).